KRAS (KRas proto-oncogene, GTPase)
Diseases named in the same sentence as KRAS in open-access papers (continued):
Sharing a sentence is not in itself a finding about the gene and the disease.
adenocarcinoma (continued). "Further analysis revealed that EML4-ALK was present at a frequency of 16.13% (10/62) in patients with adenocarcinomas, 19.23% (10/52) in never-smokers, and 42.80% (9/21) in patients with adenocarcinomas lacking EGFR and KRAS mutations." (PMID 20624322, 2010). "The clinical features of lung cancers carrying mutations in the echinoderm microtubule associated protein-like (EML4)-ALK fusion gene include mild or never smoking, younger age, adenocarcinoma with an alveolar pattern or impression ring adenocarcinoma, and lack of EGFR or KRAS mutations." (PMID 40136367, 2025). "Furthermore, in vitro cellular experiments were conducted to evaluate the suppression of KRAS expression attained by the various ASOs in NCI-H460 human adenocarcinoma cells without the use of transfection reagents." (PMID 39942684, 2025). "Biologically, these adenocarcinomas differ greatly from adenocarcinomas seen in ever smokers, with differences in the proportion of oncogenic driver mutations such as EGFR, KRAS, and BRAF; these seem to predominate in never smokers, females, and those of east Asian descent." (PMID 39125735, 2024). "They indeed confirmed this hypothesis by studying the effects of P38 pharmacological inhibition on cell growth in the EGFR mutant (delE746_A750) adenocarcinoma cell line (HCC827), which is derived from never smokers that do not harbour the KRAS mutation." (PMID 37686122, 2023). "Unexpectedly, no drug synergy was detected in several adenocarcinoma cell lines harboring mutant KRAS (right), suggesting RAS-dependent activation of mTORC1 may be specific to MM." (PMID 36115844, 2022). "Other examples of carcinogenic drivers for adenocarcinoma include modifications in protein kinase B (AKT), BRAF, human epidermal growth factor receptor-2 (HER2), phosphatidylinositol-4,5-bisphosphate 3-kinase catalytic subunit alpha (PIK3CA), MET, ROS1, RET, and KRAS." (PMID 35004079, 2022). "A study was performed with a customized NGS panel (called SiRe) including six genes [EGFR, KRAS, NRAS (NRAS Proto-Oncogene, GTPase), BRAF, KIT Proto-Oncogene Receptor Tyrosine Kinase (KIT)), Platelet-Derived Growth Factor Receptor Alpha (PDGFRA)] for 194 patients with advanced adenocarcinomas." (PMID 33922637, 2021). "Of the adenocarcinoma patients tested, 6/6 were negative for EGFR (epidermal growth factor receptor) mutation, 2/3 were ALK (Anaplastic lymphoma kinase gene) positive, and 1/5 were KRAS (Kristen rat sarcoma viral oncogene) mutant." (PMID 32754271, 2020). "Furthermore, useful data on EGFR‐, KRAS‐, ALK‐ and ROS‐mutational status of the adenocarcinoma subcohort is not present and fresh frozen tissue is no more attainable." (PMID 31760702, 2020). "Conversely, let-7g was dramatically downregulated in EGFR/KRAS negative adenocarcinomas." (PMID 26273639, 2015). "In non-serrated adenocarcinomas, MSI-H and KRAS mutations did not co-occur (P = 0.278)." (PMID 21457162, 2011). "As KRAS mutations are common, but KRAS itself is not a druggable target, our finding that H3K9 KDMi decreases expression of genes associated with oncogenic KRAS suggests that H3K9 KDMi represents a viable personalized therapy for patients with KRAS-mutated adenocarcinoma." (PMID 30455465, 2018).
adenocarcinoma (continued). "In our investigated cohort of triple-negative NSCLCs (EGFR, KRAS, and BRAF mutation negative) the number of cases with either ROS1 or RET fusions were similar to that of ALK-positive cases, supporting the need of multiplexed gene fusion diagnostics in NSCLC and adenocarcinoma specifically." (PMID 28415793, 2017). "In addition, these findings confirm the expected ability of mutant RAS to render EGFR-mutant adenocarcinoma cells resistant to TKI's and further enhance the significance of not observing oncogenic KRAS mutations in human tumors resistant to erlotinib (see ‘Discussion’)." (PMID 26047463, 2015). "APC, KRAS, and CDKN2A were focused on in the present study, and cases with adenocarcinomas were classified based on the presence or absence of each alteration." (PMID 38672586, 2024). "The GG group was characterized by predominantly stage IIIBwet/IV (82.2%), adenocarcinoma histology (70.0%), former or never smoking habit (67.8%), ECOG-PS of 0 (58.9%) and a wild-type status of KRAS (75.5%)." (PMID 27966655, 2016). "I therefore believe that KRAS and EGFR testing should be available in adenocarcinoma patients, because “adenocarcinoma” is not a unitary entity." (PMID 19672420, 2009). "Seventeen studies aimed at predicting EGFR status, one aimed at predicting ALK status, three at predicting both EGFR and KRAS status, one at identifying ALK/ROS1/RET fusion-positive versus fusion-negative adenocarcinomas and two at predicting the PD-L1 expression level." (PMID 32486314, 2020). "Our study suggested that solid-predominant tumors had the highest expression of Mean/MWV among the various histologic subtypes, but the number of genomic triple negative adenocarcinoma was not significantly higher than that of adenocarcinoma harboring exclusive gene of either EGFR, KRAS, or ALK." (PMID 29535840, 2018). "Similarly, the AG/AA patients were predominantly high stage (80.8%), with adenocarcinoma histology (70.2%), former or never smoking habit (66.0%), ECOG-PS of 0 (51.1%) and a wild-type status of KRAS (80.8%)." (PMID 27966655, 2016).
infection (371 papers, 2006 to 2026). The state of being infected such as from the introduction of a foreign agent such as serum, vaccine, antigenic substance or organism. "Our research systematically describes the impact of miR3655 against the backdrop of KRAS mutations and infection of ETBF on CRC, revealing innovative value as a new biomarker and potential therapeutic target." (PMID 39523457, 2024). "Lentivirus particles were produced and infected into HEK293T/17 cells with a low multiplicity of infection to introduce only one type of KRAS mutation per cell." (PMID 37391511, 2023). "Massive cell death, in a dose-dependent manner, was induced following infection of HCT116 cells [containing a mutated KRAS at codon 13 (Gly to Asp)] with Ad-Py4-SV40-mCherry-MazF." (PMID 28445136, 2017). "Further, our investigation with KRAS mutated HCT116 cell line showed that effective expression of host TLR3 dampens the infection potential of reovirus by mounting a robust innate immune response." (PMID 28422714, 2017). "We showed that C2 could be adapted to in vivo colonization through just 1 week of infection in the KRAS+ stomach by selecting for a lower frequency allele at the sabB locus." (PMID 36598261, 2023). "In addition, in HCT116 cells, which express a wild-type and a mutant Kras allele, infection with lenti-shSIRT2 increased both KRAS activity, as evidenced by increased pERK levels, and colony formation, as revealed by enhanced growth in soft agar." (PMID 27637077, 2016). "Moreover, both KRAS mutations and FN infection suppress the expression of SERTAD4." (PMID 39462261, 2024). "Consistently in vivo, KRAS (labeled with Cy3) in BMECs (labeled with anti-CD31-FITC) of mice treated with TGFβ1 prior infection was downregulated, in contrast to those left untreated." (PMID 38360663, 2024). "To recapitulate the molecular events underlying PDAC initiation, we first overexpressed oncogenic KRASG12V in wild-type acinar organoids (referred to KRAS organoids) by lentiviral infection with a vector containing KRASG12V-mCherry." (PMID 38280869, 2024). "KRAS in hBMECs was downregulated upon infection because of rTGFβ1 treatment, while it was upregulated in the presence of GANT61." (PMID 38360663, 2024). "In summary, as a new molecule that can predict diagnosis and prognosis of CRC, KRAS mutations, and ETBF infection both suppress the expression of miR3655 in CRC." (PMID 39523457, 2024). "In support of the association of Fn with MSI-H or KRAS mutations, although indirect, Ternes and colleagues showed that Fn infection is significantly enriched in CMS1 where 74% are MSI-H and in CMS3 where 70% carry KRAS mutations." (PMID 37772997, 2023). "If this is the case, Fn infection must be associated with two sets of hypermethylated TSGs, one such as MLH1 is accompanied with BRAFV600E and another is accompanied with KRAS mutations." (PMID 37772997, 2023). "To confirm that Hp was responsible for inducing inflammation that drove metaplastic pit cell expansion, we tested samples from Hp+KRAS+ mice given antibiotics from 6 to 8 weeks after infection and constitutively active KRAS induction." (PMID 37674528, 2023). "For comparison, we also tested KRAS+ mice with PMSS1 or mock infection (from a previous study and two additional replicates for this study)." (PMID 36598261, 2023). "Nonetheless, within our controlled experiments, TROP2 staining was greatest in Hp+/KRAS+ mice, suggesting that infection accelerates the onset of dysplasia." (PMID 33310760, 2021). "Consistently, RNA sequencing from the lungs of Ad5-hACE2 vs Ad5-empty mice at 3 DPI revealed that interferon (Ifn)-gamma and alpha, allograft rejection, complement and KRAS signaling are upregulated in response to SARS-CoV-2-infection." (PMID 34307198, 2021).
infection (continued). "Tissue histology, gene expression, the immune cell repertoire, and metaplasia and dysplasia marker expression were assessed in KRAS+ mice +/−Hp infection." (PMID 33310760, 2021). "Briefly, cells were harvested for RNA and genomic DNA 4 to 7 days following infection with lentivirus shRNA targeting KRAS." (PMID 32576853, 2020). "We observed a decrease in Treg-like cell conversion after infection with live bioluminescent Salmonella compared to MT KRAS TDEs." (PMID 31635338, 2019). "The expression of mature miR-16 was observed to be 8-10-fold higher after infection, and KRAS protein expression was consequently inhibited." (PMID 27857191, 2016). "Additionally, we performed further characterization of the indel distribution, infection efficiency, and KRAS targeting in all three resistant cell lines." (PMID 40890128, 2025). "However, the association between TROP2 and KI-67 was greatest in Hp+/KRAS+ mice at 12 wk, where a median of 86% of TROP2+ glands or gland fragments were KI-67+ (P < 0.01), suggesting that Hp infection increases the proliferation of dysplastic glands." (PMID 33310760, 2021). "To assess whether Hp impacts KRAS-driven metaplasia, we performed concomitant infection/induction experiments in Mist1-Kras mice." (PMID 33310760, 2021). "Interestingly, we found that a few Hp+/KRAS+ mice naturally cleared their infection, yet still had a high degree of immunopathology." (PMID 33310760, 2021). "We observed exponential growth of the KCST primary spheres over 5 months, while the spheres transduced with lentiviruses encoding Control-NeoR, KRAS-NeoR-Neo alone or a mixture of control viruses (CTRLmix) failed to expand beyond 30 days after infection." (PMID 28272465, 2017). "Interestingly, co-infection of SLC22A18 virus with KRAS virus led to a significant decrease in the number of visible multicellular colonies." (PMID 26196590, 2015). "Other pathways with significant time × severity interactions included “KRAS signaling” and “MYC targets” in B cells, likely reflecting time-dependent changes in their proliferation during infection that vary according to severity." (PMID 40532694, 2025). "Contrarily, has-miR-155 mimics repressed the KRAS expression and ERK1/2 activity in hBMECs upon infection, subsequently attenuating the expression of IL-6, MIP-2, and E-selectin." (PMID 38360663, 2024). "Specifically, the expression levels of KRAS and BRAF, upstream components of the MAPK/ERK pathway, were upregulated at the early stage (3 and 6 h) of the infection." (PMID 33425779, 2020). "The KRAS mutant HCT116 and KRAS WT Hke3 cells were infected with reovirus 5MOI and harvested at 48 hours post infection, with treatment with 10uM BrdU 1 hour prior to harvest." (PMID 24798549, 2014). "After infection with KRAS-mCherry lentivirus, there was an upregulation of YAP1/TAZ and their targets, suggesting that KRAS may induce YAP1/TAZ expression." (PMID 38247878, 2024). "Moreover, we knocked down SLC25A21 expression in KRAS-mutant HCT116 and SW480 cells and in KRAS-WT HT29 cells, which have relatively high endogenous expression, by infection with a lentiviral vector harboring shRNA-SLC25A21." (PMID 37937641, 2023). "HOC-7 cell lines have the KRAS mutation, presumably keeping activated the MAPKs pathway, showed phosphorylation of MEK after infection of IkBαM, while SKOV3 cell line, which sequenced to be the KRAS wild type, showed dephosphorylation of both MEK and ERK following the infection of IkBαM." (PMID 27484466, 2016). "However, some genes, such as Jak2, Notch2, and Runx1, were up-regulated in KRAS+ mice regardless of infection status." (PMID 33310760, 2021).
colorectal (66 papers, 2001 to 2025). "Aberrant regulation of the Wnt signaling pathway is an established mechanism of colorectal carcinogenesis, however, its association with KRAS status is controversial." (PMID 34108518, 2021). "Ninety-three percent (13/14) of FBXW7 mutations detected were missense as were all six KRAS mutations, with three due to a substitution of glutamine to histidine (Q61H), a mutation mainly reported in colorectal malignancies." (PMID 32520976, 2020). "The results of our study also showed that patients with KRAS mutation had a higher frequency of both lung and liver metastases at the time of bone metastasis." (PMID 33273596, 2020). "KRAS-mutations are one of the most common genetic events in lung ADC and constitutively activate effectors downstream of EGFR, thus they can potentially cause TKI-resistance and be a negative predictive biomarker for response to EGFR-TKIs in NSCLC." (PMID 29899852, 2018). "Our inferred hierarchy from somatic mutations suggested that KRAS mutations were the earliest events in colorectal carcinogenesis." (PMID 29697365, 2018). "Despite these assumptions, our data suggest that an early DNA methylation event may commit the primary tumor to particular genomic trajectories, as suggested for MGMT hypermethylation preceding KRAS activating mutations in colorectal cancer." (PMID 40931149, 2025). "Notably, LTB4R2 was also identified in our previous work as a dependency gene specifically associated with the KRAS-mutated background in lung AD." (PMID 34298691, 2021). "However, the relationship between high-frequency KRAS mutations and metaplastic differentiation remains unclear in colorectal precancerous lesions." (PMID 41018078, 2025). "Although further clinical investigations will be required, our data suggest that those lung AC patients harbouring KRAS mutations or a known smoking history (as a surrogate marker for KRAS mutations), may not respond to STAT3 inhibitors but may likely suffer severe adverse effects." (PMID 25734337, 2015). "In lung ADC, KRAS mutation is found in about 32% of the cases and, of these, the KRAS-G12C mutation is the predominant, occurring in 46% of the cases." (PMID 34198671, 2021). "Total IκBα, which is an NF-κB-activated gene, was also increased by 2.32-fold and 1.62-fold, respectively, indicating increased activity of the IKK/NF-κB pathway in KRAS-positive lung tumourspheres enriched for TIC activity." (PMID 32823550, 2020). "One important mechanism driving lung tumourigenesis is the KRAS-mediated activation of the nuclear factor kappa-B (NF-κB) transcription factor." (PMID 32823550, 2020). "Taken together these results provide independent confirmation that the ER-α is highly activated in a subpopulation of KRAS MT lung ADs." (PMID 26468985, 2015). "This study explored the signaling network of KRAS mutant (MT) lung ADs to identify therapeutic biomarkers for the development of targeted treatment for this subgroup of patients." (PMID 26468985, 2015).
colorectal (continued). "Accumulation of molecular alterations, including EGFR overexpression and mutations in KRAS and BRAF, contribute to colorectal carcinogenesis." (PMID 23459231, 2013). "Our results show that BRAF, KRAS and PIK3CA mutations occur prior to malignant transformation demonstrating that these oncogenic alterations are primary genetic events in colorectal carcinogenesis." (PMID 18782444, 2008). "Overall survival (OS) for Stage IV lung ADC at initial diagnosis were analyzed in patients with BRAF V600E or with undetected mutation (no driver mutation/fusion detected in BRAF, EGFR, KRAS, ALK, ROS1, RET, HER2, or MET genes)." (PMID 31234388, 2019). "In conclusion, our results show that mutations of BRAF, KRAS and PIK3CA occur in non-malignant lesions of colorectum demonstrating that these oncogenic alterations are primary genetic events in colorectal carcinogenesis." (PMID 18782444, 2008).